CRY2 (cryptochrome circadian regulator 2)
Diseases named in the same sentence as CRY2 in open-access papers (continued):
Sharing a sentence is not in itself a finding about the gene and the disease.
cancer (continued). "This suggests that Cry2 may play a more dominant role than Cry1 in altering cancer-related signaling pathways." (PMID 37024472, 2023). "Although circadian clock disruption is related to various cancer types, the loss of Cry1 and Cry2 caused an unexpected effect on cancer and did not aggravate the radiation-induced tumor growth and mortality." (PMID 36347873, 2022). "Previous studies have also confirmed the opposite effects of NPAS2 and CRY2 on cancer prognosis." (PMID 35832846, 2022). "In addition, CRY2 has been suggested to act as a modulator in the development of cancer." (PMID 29513728, 2018). "For example, CRY2, part of the SCFFBXL3 complex, promotes the ubiquitination of c-MYC, inhibiting growth in cancer cells." (PMID 39566400, 2024). "GEPIA was used to understand the messenger (m)RNA expressions of circadian rhythm-related factors in the PER family (PER1, PER2, and PER3), CRY family (CRY1 and CRY2), BMAL1, and CLOCK in different types of cancer." (PMID 36385012, 2022). "Among them, certain rhythm genes such as DBP, CRY2, and CIART are protective effectors for the prognosis of most cancers, whereas certain rhythm genes such as TIMELESS and SERPINE1 are risk factors for the prognosis of most cancer." (PMID 31927791, 2020). "We demonstrated that in vitro and in vivo cancer cells after PER1 knockdown, PER2, DEC1, DEC2, CRY1, CRY2 and NPAS2 were significantly down-regulated at the mRNA level, while PER3, TIM, RORα and REV-ERBα were significantly up-regulated." (PMID 27602964, 2016). "In addition, given the evidence that response to cancer therapy may be influenced by circadian cycling, and the fact that CRY2 may influence the accumulation of DNA damage, future investigations into the effects of CRY2 on response to treatment are also warranted." (PMID 20334671, 2010). "Concerning CRY2, to our knowledge, there are no reports to date describing any anti-cancer activity of the only existing CRY2-specific stabilizer, TH301." (PMID 39796036, 2024). "Interestingly, down-regulation of PER1-3, CRY2, NPAS2, BMAL1, as well as CLOCK gene expression, correlates with high histological grade and poor prognosis and short survival in different cancers." (PMID 36672355, 2023). "The PER1, PER2, and PER3 genes regulate cell growth, proliferation, and apoptosis, CRY1 and CRY2 regulate the transcription G1/S and G2/M cell cycle checkpoints, while BMAL1 and NPAS2 inhibit the proliferation and invasion of cancer cells by suppressing the c-Myc transcription factor." (PMID 36672355, 2023). "In addition, it was shown that Cluster 1 (CRY2, PER1, and RORA) and TIMELESS exerted opposite impacts on interactive gene network, infiltration of immune cells, cancer-related signaling pathways, and cellular sensitivity to clinically used drugs." (PMID 34745328, 2021). "Besides, CRY2, PER1, and RORA exerted opposite impacts against TIMELESS on immune cell infiltration and cancer-related signaling pathways, affecting the overall survival of HCC patients." (PMID 34745328, 2021). "Meanwhile, others clock genes were downregulated including PER1 in 11 cancer types, PER2 in 7, PER3 and CRY2 in 10 and RORα in 11, indicating they may act as tumor suppressor genes." (PMID 33042011, 2020). "The two datasets with the highest ΔCCD (>50% higher than any ΔCCD we observed in human cancer) were those in which the knockout mice lacked not one, but two components of the clock (Cry1 and Cry2 in GSE13093; Nr1d1 and Nr1d2 in GSE34018)." (PMID 29404219, 2018).
cancer (continued). "Quantitative real-time PCR result indicated that in vitro and in vivo cancer cells after PER1 knockdown, PER2, DEC1, DEC2, CRY1, CRY2 and NPAS2 were significantly down-regulated at the mRNA level, while PER3, TIM, RORα and REV-ERBα were significantly up-regulated." (PMID 27602964, 2016). "This study demonstrates that the down-regulation of PER1 in cancer cells can result in the robust up-regulation of PER3, TIM, RORα and REV-ERBα transcripts, while the expression of PER2, DEC1, DEC2, CRY1, CRY2 and NPAS2 is prominently down-regulated in vitro and in vivo." (PMID 27602964, 2016). "CRY2 was absent in the nucleus in cancer cells and low in the cytoplasm, while neighbouring and normal mucosal cells showed no major differences." (PMID 27465361, 2016). "Another study of Cry1-/-Cry2-/- also showed that while these mice were significantly smaller than their WT counterparts, they did not have any obvious malignancies, and they remained reproductively fit." (PMID 20334671, 2010). "Future investigations may wish to focus on the transcriptional influence of CRY2 on oncogenic CCND1, and the relationship with CDKN1A, as these findings have the potential for broad impact on a number of cancer types." (PMID 20334671, 2010). "Finally, several SNPs in genes of the circadian rhythm unexplored with cognition previously were evaluated in cancer patients: rs1801260 in CLOCK (Circadian Locomotor Output Cycles Kaput), rs934945 in PER2 (Period circadian regulator 2), and rs10838524 CRY2 (Cryptochrome circadian regulator 2)." (PMID 36123640, 2022). "In order to achieve a systematic understanding of circadian clock in cancer, we define a core subset of clock family genes including 7 positive regulators (CLOCK, NPAS2, ARNTL, ARNTL2, RORA, RORB, and RORC) and 7 negative regulators (PER1, PER2, PER3, CRY1, CRY2, NR1D1, and NR1D2)." (PMID 31708917, 2019). "If in fact reduced CRY2 results in increased DNA damage without triggering increases in cell death or apoptosis, this could potentially lead to cancer, as damaged cells could survive and be allowed to proliferate." (PMID 20334671, 2010). "However, Cry1-/-, Cry2-/- transgenic mice do not display a cancer-prone phenotype in response to ionizing radiation exposure." (PMID 20334671, 2010). "Among 716 samples across 29 cancer types, we interestingly observe that most of the negative regulators, such as PER1, PER2, PER3, CRY1, CRY2, and NR1D2, are down-regulated in a wide range of cancers." (PMID 31708917, 2019).
tumor (48 papers, 2010 to 2025). "When Panther pathway analysis was performed separately for tumour suppressors and oncogenes, interestingly, biological process rhythmic process (GO:0048511) and pathway circadian clock system (P00015) were linked only to tumour-suppressor genes (CRY2 and FBXL3)." (PMID 34198662, 2021). "Additionally, Cry1 and Cry2 mutations alter tumor formation." (PMID 37024472, 2023). "BMAL1 drives the transcription of VEGFA conferring resistance to bevacizumab treatment, therefore combining bevacizumab with a CRY2 stabilizer (SHP1705) to inhibit BMAL1 activity led to a decreased tumor volume and an improved OS in mouse models." (PMID 39199569, 2024). "Overall, the roles of Cry1 and Cry2 in regulating tumor formation or progression are distinct and unique; therefore, their potential functions in tumor development must be examined separately." (PMID 37024472, 2023). "Numerous studies have shown that circadian rhythm regulators, such as PER2, CLOCK, BMAL1, CRY1, and CRY2, act as tumor suppressors in the liver, ovaries, colon, and lung." (PMID 37524704, 2023). "Only Cry2 stimulates the degradation of the critical tumor activator MYC by recruiting it to SCFFBXL3, whereas Cry1 does not." (PMID 37024472, 2023). "Per1-/-, Per2-/-, Cry1-/-, Cry2-/- andBmal1-/- mice presented with increased spontaneous and radiation-induced tumor development." (PMID 39282509, 2023). "Collectively, our findings indicate that KDM4B promotes tumor progression through the miR-181d-5p/SCFFBXL3+CRY2/MYC axis." (PMID 38093312, 2023). "MCF7 cells stably transfected with Cry2-WT, Cry2–3KR, Cry2–3KQ, or the control vector were inoculated into nude mice in a xenograft assay to test the tumor-suppressing role of Cry2." (PMID 37024472, 2023). "Cryptochrome 2(CRY2) was identified to be a tumour suppressor and upstream inhibitor of oncogenic c‐MYC." (PMID 36162823, 2023). "As for CRY2, its impairment in mouse fibroblast carries into an increased expression of c-Myc, resulting in greater cell growth, proponing its contribution to tumor limitation through c-Myc turnover." (PMID 35897788, 2022). "We then identified which immune cells subtypes present in the tumor infiltration were associated with the expression of the three CCGs, PER-1, CRY2, and NPAS2 and the prognosis of HCC." (PMID 36118525, 2022). "Collectively, these findings establish NanoLOGS as a safe wireless method to effectively activate CRY2‐based optogenetic devices to kill tumor cells both in cellulo and in vivo." (PMID 34540558, 2021). "Specifically, we observed reduced expression of the Per2 and Cry2 clock genes in primary tumours of JL mice." (PMID 32581213, 2020). "We also observed a decrease of Per2 and Cry2 expression in primary tumours of JL mice while expression levels of other core clock genes remained similar between treatments." (PMID 32581213, 2020). "Nearly ten years later, another unexpected regulatory function between FBXL3 and CRY2 is found that FBXL3 in cooperation with CRY2 targets an oncogenic substrate c-Myc to inhibit uncontrolled tumor cell growth." (PMID 32226545, 2020). "We observed that core clock genes, PERs, CRY2, CLOCK, NR1D2, RORA and RORB exhibited global patterns of somatic loss and downregulation across multiple tumour types." (PMID 31014368, 2019). "Of the seven-downregulated genes studied, the CRY2 was the most downregulated gene, a nine times decrease in tumor tissue compared to the non-tumor tissue was measured." (PMID 31151182, 2019).
tumor (continued). "Several clock genes showed a down-regulation when compared to their own neighbouring mucosa, i.e. PER1, PER2 and PER3, while CRY2 was down-regulated in both tumour and neighbouring tissue when compared to normal mucosa from unrelated donors." (PMID 27465361, 2016). "CRY1 (p = 0.01) and CRY2 (p < 0.0001) expression was significantly changed in tumour tissue, as confirmed in a large independent CRC dataset." (PMID 26768731, 2016). "Among the clock genes, the expression of PER1, PER2, PER3 and CRY2 were significantly elevated in the benign tissue compared to the tumour tissue (p = 0.001, 0.002, 0.037 and 0.001 respectively)." (PMID 27465361, 2016). "After stratifying patients according to the median value of gene expression, subjects with CRY1 (p = 0.042) and CRY2 (p = 0.043) tumour mRNA levels above the median showed poorer survival rates in a Kaplan–Meier analysis of censored data." (PMID 26768731, 2016). "In contrast, lower CRY1 and CRY2 expression was found in tumour tissues located at the transverse colon." (PMID 26768731, 2016). "For CRY1, the gene seemed to be equally up- or down-regulated in the samples, and for CRY2, the majority of the samples showed a down-regulation in the tumour tissue." (PMID 27465361, 2016). "Genetic inactivation of Cry1 and/or Cry2 has also been reported to alter rates of tumor formation, though the reported effects have varied." (PMID 25756610, 2015). "CRY2 codes for a flavin adenine dinucleotide-binding protein that acts as a regulator of the circadian clock, and may promote growth of tumor cells." (PMID 36439444, 2022). "Moreover, the mRNA expression of CLOCK, CRY1, and CRY2 declined in tumor tissues compared with normal tissues (p < 0.001)." (PMID 32681792, 2020). "Unlike CRY DKO mice, loss of CRY2 alone induces increased tumor burden and enhanced susceptibility to transformation, supporting an unexpected function of CRY2 in contributing to circadian protection from tumor formation." (PMID 33114365, 2020). "Additionally, lower CRY1 mRNA levels were found in female CRC patients, while higher CRY1 and CRY2 levels were observed in tumours located at the distal colonic segments (descending and sigmoid colon, rectum)." (PMID 26768731, 2016). "The transfection of mCh‐NanoLuc‐CRY2 alone did not cause cell death within 30 min after Fz treatment, fully demonstrating the general applicability of LiPOP1‐NanoLuc for tumor killing in vitro." (PMID 34540558, 2021). "Immunohistochemical analysis of tumor tissues showed that MYC expression was downregulated after KDM4B knockdown, while FBXL3 and CRY2 expression was upregulated." (PMID 38093312, 2023). "When stratifying for tumour grade, 17 genes were found to have a significant effect survival, of which four core-clock genes (BMAL1/2, CRY2 and RORC)." (PMID 37400829, 2023). "On the contrary, CRY2 and DBP inhibited DNA damage and cell cycle pathways to enhance tumor cell growth." (PMID 35832846, 2022). "The expression of CRY2, PER2, PER3 and RORA was correlated with TNM stage, T stage, and tumor differentiation in KIRC patients (p < 0.05)." (PMID 34977153, 2021). "PER1, PER2, PER3, CRY2 were found to be significantly down-expressed, while CLOCK, TIMELESS were over-expressed in the studied tumor samples compared to the non-tumor samples." (PMID 29958276, 2018). "It works together with CRY2 to degrade the C-MYC protein, which helps prevent tumor growth." (PMID 40313868, 2025). "circMYC could sponge tumor suppressing miR-20b-5p and let-7e-5p, hence influencing their downstream targets, argonaute RISC component 1 (AGO1) and cryptochrome circadian regulator 2 (CRY2), affecting tumor progression." (PMID 35311066, 2022). "FBXL3 mediated degradation of CRY1 and CRY2 can re-activate the CLOCK-BMAL1 complex and increase the protein levels of period circadian protein homolog 1 (PER1) and 2 (PER2), two circadian clock regulators with tumor suppressor activity." (PMID 32226545, 2020).
tumor (continued). "CRY1 (median = 0.73, Q1-Q3 = 0.43-1.24, p < 0.01) and CRY2 (median = 0.50, Q1-Q3 = 0.25-0.77, p < 0.001) mRNA levels showed a statistically significant decrease in tumour tissues in comparison to matched non-tumorous tissues." (PMID 26768731, 2016). "Consistently, CRY1 and CRY2 protein levels decreased in tumour tissues compared to the non-tumorous counterpart in a panel of matched specimens." (PMID 26768731, 2016). "CRY1 and CRY2 mRNA levels were assessed in 50 pairs of tumour tissue/non-tumorous mucosa comprising 46 well-moderately differentiated (G1-G2) and 4 poorly differentiated-undifferentiated (G3-G4) CRCs." (PMID 26768731, 2016). "In the tumor tissue, CRY1, TIM, and GPER1 expressions showed circadian rhythms in both the control and the TRF groups, but the circadian rhythm of TIM expression was more robust in the TRF group, while CRY2 were acyclic in the control group and FBXL3 were acyclic in the TRF group." (PMID 37924048, 2023). "Previously, we observed downregulation of cry2 and per2 expression in tumour tissue in comparison to adjacent tissue, and higher expression of cry1 in right-sided tumours but not in left-sided tumours compared to surrounding tissue." (PMID 36361993, 2022). "Indeed, CRY2, PER1, and RORA were downregulated, and TIMELESS was upregulated in tumor tissues, suggesting that TIMELESS may play a different role in HCC." (PMID 34745328, 2021). "CRY1 and CRY2 mRNA levels were significantly changed in CRC tissue when compared to matched non-tumorous mucosa, and there was a positive linear correlation between mRNA expression levels of both cryptochrome genes, probably indicating a corresponding and parallel alteration in tumour tissues." (PMID 26768731, 2016). "This is especially notable given that CRY2- cells do not exhibit decreased survival or increased apoptosis, suggesting that they survive equally well despite the increased level of DNA damage; a phenotype which could lead to tumor promotion." (PMID 20334671, 2010).
metabolic disease (5 papers, 2016 to 2025). A congenital disorder (due to inherited enzyme abnormality) or acquired (due to failure of a metabolically important organ) disorder resulting from an abnormal metabolic process. "Dysfunction of CRY1 and CRY2 isoforms has been associated with a host of diseases, such as sleep phase disorder and metabolic diseases." (PMID 35153842, 2022). "In whole-body Cry1 and Cry2, as well as in liver-specific Arntl and Reverbα/β knockout mice, TRF protected mice from excessive weight gain and metabolic diseases compared to both WT and clock gene KO mice that were fed ad libitum." (PMID 34836101, 2021).
degenerative diseases (2 papers, 2020 to 2021). "These include Spon2, Adam19, Arntl, Cdkn1a, Cry2, Per2, Per3, Wee1, Rcan1, Slc41a3, Errfi1, and Bhlhe41, which are related to numerous cardiovascular and degenerative diseases of other organs as well as varying aging processes." (PMID 33668521, 2021). "Melatonin increases the expression levels of cryptochrome 2 (CRY2), period circadian protein homologue 1 (PER1) and brain muscle ARNT-like 1 (BMAL1), which are associated with neurodegenerative diseases." (PMID 32784556, 2020).
neurological disorders (1 paper, 2017). "Three genes are involved in developmental and neurological disorders: C3orf36, CDK5RAP2, CRY2." (PMID 29259192, 2017).
CRY2 also shares sentences with these, for which no sentence is quoted: psychiatric disorder (4 papers); glioblastoma (2); schizophrenia (2); adenoma (1); alcohol (1); bladder cancer (1); chronic lymphocytic leukemia (1); fibrosarcoma (1); gastric cancer (1); glaucoma (1); head and neck cancer (1); hyperaldosteronism (1); Insulin resistance (1); liver cancer (1); liver fibrosis (1); malignant brain tumor (1); marginal zone B-cell lymphoma (1); metastatic melanoma (1); mood disturbances (1); mucopolysaccharidosis type 2 (1); multiple sclerosis (1); non-alcoholic fatty liver disease (1); non‐alcoholic steatohepatitis (1); oculocerebrorenal syndrome of Lowe (1); Parkinson disease (1); primary aldosteronism (1); psoriasis (1); rectal cancer (1); sarcoma (1); Sepsis (1).
A further 7 diseases each share a sentence with CRY2 in 1 paper.